IFNG (interferon gamma)
Diseases named in the same sentence as IFNG in open-access papers (continued):
Sharing a sentence is not in itself a finding about the gene and the disease.
kidney infection (4 papers, 2011 to 2022). "T cells are the predominant cell type responsible for the production of interferon gamma (IFN-γ), which limits BKPyV replication in kidney cells and is necessary for effective control of MuPyV kidney infection." (PMID 36341713, 2022). "Our next aim was to define if the spleen was the primary contributor to the detected serum IFNγ by performing a complete splenectomy prior to kidney infection." (PMID 34015044, 2021). "Further confirming that the spleen was producing IFNγ following kidney infection, ELISA analysis of spleens from infected, sham-splenectomised animals displayed significantly higher IFNγ levels compared to those infused with PBS." (PMID 34015044, 2021). "Combining our model with tissue transcriptomics, we showed that within 8 h of UPEC infection there was an overrepresentation of interferon-γ (IFNγ) regulated genes expressed at the kidney infection site." (PMID 34015044, 2021). "This suggests that IFNγ has a potential to enhance immunosurveillance and the response to bacteria during kidney infection." (PMID 34015044, 2021). "During kidney infection, IFNγ stimulation has been shown to increase TLR4 and TLR2 expression in infected kidneys." (PMID 34015044, 2021). "In combination with our previous transcriptomic data, which showed a significant increase in a number of IFNγ regulated genes during kidney infection, this work highlights an important modulatory role of splenic IFNγ within the first hours of kidney infection." (PMID 34015044, 2021). "Unexpectedly, the IFNγ we detected in the serum of animals with kidney infection appeared to originate from the spleen, implying some type of inter-organ communication." (PMID 34015044, 2021). "While we had identified HlyA as a bacterial factor triggering nerve-driven communication between the kidney and the spleen, the question remained, what is the role of splenic IFNγ in local kidney infection?" (PMID 34015044, 2021). "Together this data revealed that the spleen produces IFNγ within 4 h of a local kidney infection, and that it is the major contributor to the observed systemic IFNγ." (PMID 34015044, 2021). "IFNγ can then modulate inflammation in infected renal epithelial cells, demonstrating a role for nerves in the early coordinated host response to kidney infection." (PMID 34015044, 2021). "To investigate which areas in the spleen produced IFNγ during kidney infection, we performed immunohistological analysis on spleens from sham-splenectomised animals and identified IFNγ predominantly in the red pulp and marginal zones of infected, but not PBS infused animals." (PMID 34015044, 2021). "The lack of direct IFNγ release from the infected renal epithelial cells and the absence of IFNγ in infected renal tissue, further highlighted the spleen as the major producer of IFNγ during kidney infection." (PMID 34015044, 2021). "Together this suggested that the induction of splenic IFNγ in response to kidney infection was not being mediated by the typical cytokine inflammatory pathways." (PMID 34015044, 2021).
Mycobacterium avium infection (4 papers, 2012 to 2023). "In an in vivo mouse model of Mycobacterium avium infection, chronic infection triggers IFNγ-mediated proliferation of both LT-HSCs (CD34−Flk2− LSK or CD150+LSK) and ST-HSCs (CD34+Flk2−LSK)." (PMID 32373117, 2020).
osteonecrosis (4 papers, 2017 to 2023). A none disease characterized by death of bone tissue due to a lack of blood supply. "Furthermore, SARS-CoV-2 infection causes an increase in inflammatory cytokines such as C-X-C motif–chemokine 10 (CXCL10), interferon gamma (IFN-γ), interleukins (ILs) 1 beta, 6, 8 and 17, and tumor necrosis factor alpha (TNF-α), resulting in bone mineral loss, osteonecrosis and chondrolysis." (PMID 36984576, 2023).
otitis media (4 papers, 2009 to 2024). Inflammation of the anatomical structures of the middle ear, which is most often caused by an infectious process. "Genetic variants at IFNG are associated with risk for otitis media in infants infected with the respiratory syncytial virus (RSV)." (PMID 19728873, 2009). "Previous candidate gene studies associated a number of immune system genes with otitis media, which included TNF-α, IL-6, IL-10, Tlr4, surfactant, CD14, FcγRIIa, IFNγ, Eya4, p73, MyD88, Fas, E2f4, Plg, Fbxo11, and Evi1." (PMID 24466073, 2014). "Kadilya established a rat model of otitis media and reported that kukoamine A could alleviate inflammation in rats by reducing the levels of inflammation-related cytokines, such as interleukin-4 (IL-4), interferon-gamma (IFN-γ), and tumor necrosis factor-α (TNF-α), in a dose-dependent manner." (PMID 39473702, 2024). "When RSV-induced and non-RSV-induced otitis media cases were compared, significantly higher levels of IFNG were found in the RSV-induced cases." (PMID 19728873, 2009).
pharyngitis (4 papers, 2019 to 2025). Inflammation of the throat most often caused by viral and bacterial infections. "Individuals suffering from pharyngitis exhibited elevated levels of salivary pro-inflammatory cytokines, namely IL-1Ra, Interleukin-6 (IL-6), IFNγ, and IP-10." (PMID 40276383, 2025). "MAIT cells are highly activated to release IFNγ, IL-1β, IL-2 and TNF, which are involved in pharyngitis, invasive GAS disease and ARF." (PMID 40276383, 2025).
post-traumatic stress disorder (4 papers, 2020 to 2022). An anxiety disorder precipitated by an experience of intense fear or horror while exposed to a traumatic (especially life-threatening) event. "Furthermore, posttraumatic stress disorder was found to cause upregulation of serum interleukin 6 (IL-6) and proinflammatory cytokines, such as interferon-gamma (IFN-γ), interleukin 1 β (IL-1β), interleukin 10 (IL 10), and tumor necrosis factor α (TNF α)." (PMID 34966477, 2021). "In addition, the post-traumatic stress disorder (PTSD) is associated with increased levels of IL-6, interleukin-1 beta (IL-1β), interferon gamma (INFγ) and tumor necrosis factor alpha (TNFα)." (PMID 32858844, 2020). "The outcomes were psychological well-being [perceived stress, depressive symptoms, loneliness, and post-traumatic stress disorder (PTSD)] symptoms and stress-related markers, including diurnal salivary cortisol and cytokines interleukin-6 (IL-6) and interferon gamma (IFN-γ)." (PMID 36042095, 2022).
reovirus infection (4 papers, 2011 to 2024). "Although the dependence on NK cells could be because of their early role in recruiting sDCs to initiate anti-tumor immunity, the demonstration that the CD4+ T cells were the most potent producers of IFNg in response to reovirus infection supports their direct role in control of tumor growth." (PMID 33665363, 2021).
rhinitis (4 papers, 2021 to 2025). An inflammation of the mucous membrane lining the nose, usually associated with nasal discharge. "The mechanism by which O3 exposure causes rhinitis in rats was shown to be due to the fact that inhalation of O3 increases Th2 cytokines and reduces interferon-gamma (IFN-γ), which is a protein regulating inflammatory and immune responses." (PMID 40137523, 2025).
Schistosoma haematobium infection (4 papers, 2012 to 2021). "In humans, Schistosoma haematobium infection has been shown to lead to hypermethylation of immune system genes within CD4+ T cells, with inhibition of genes in the Th1 and IFNγ signaling pathways being observed, indicating a role for epigenetic control of the IFNγ response." (PMID 33790908, 2021).
scleritis (4 papers, 2019 to 2025). Inflammation of the sclera. "Patients with a positive interferon gamma release assay test as part of their scleritis diagnostic evaluation had been previously treated with anti-tuberculous medication." (PMID 40095049, 2025). "Moreover, histocompatibility complex (MHC), TNF, IL1A, IL1β, IL2, IFNγ, and TNF were widely present in the top five disease signaling pathways, suggesting that these genes may be involved in the development of scleritis." (PMID 37063831, 2023).
seminoma (4 papers, 2023 to 2026). A radiosensitive malignant germ cell tumor found in the testis (especially undescended), and extragonadal sites (anterior mediastinum and pineal gland). "Instead, seminoma malignancy was specifically associated with IFNG+ T cells." (PMID 41203637, 2025). "Neutrophil degranulation and Interferon gamma signalling were each identified as top‐regulated pathways in area 2 of the seminoma sample along with higher levels of immune cell subtype markers, indicating a function for localised, enhanced neutrophil activity." (PMID 40693358, 2026). "This supports the idea that effective immune surveillance, particularly via IFNG+ T cells, is crucial for confining seminomas to the primary site and limiting metastasis, whereas an immune desert microenvironment facilitates tumor progression." (PMID 41203637, 2025). "We further uncover a population of IFNG+ T cells within the immune microenvironment of seminomas that suppress metastatic progression." (PMID 41203637, 2025). "Furthermore, as we previously published, seminomas revealed high IFNG and TNF expression, while the expression of these genes were low in NSGCT." (PMID 40011822, 2025). "Additionally, IFN-γ secreted by IFNG+ T cells acts directly on seminomas, promoting differentiation and thereby inhibiting tumor progression." (PMID 41203637, 2025). "Furthermore, IFN-γ secreted by IFNG+ T cells in the non-metastatic seminoma microenvironment effectively counteracts this immunosuppressive state, restoring the functional capabilities of immune cells that attack tumor cells." (PMID 41203637, 2025). "Using TCGA mRNA expression of anabolic (CYP2R1, CYP27A1 and CYP27B1) and catabolic (CYP24A1) Vitamin D enzymes, positive (PTHLH, IFNG, and TNF) and negative (FGF23) feedback regulators could also clearly distinguish between pure seminomas and NSGCT." (PMID 37242266, 2023).
sweet syndrome (4 papers, 2007 to 2024). "Significantly elevated levels of helper T-cell type 1 cytokines (interleukin-2 and interferon-gamma) and normal levels of a helper T-cell type 2 cytokine (interleukin-4) were observed in the immunohistochemical studies of Sweet's syndrome patients' serum." (PMID 17655751, 2007). "In summary, granulocyte-colony stimulating factor, granulocyte macrophage colony stimulating factor, interferon-gamma, interleukin-1, interleukin-3, interleukin-6, and interleukin-8 are potential cytokine candidates in the pathogenesis of Sweet's syndrome." (PMID 17655751, 2007).
Takayasu arteritis (4 papers, 2019 to 2022). A rare inflammatory large-vessel vasculitis primarily affecting the aorta and its major branches, but also other large vessels, causing stenosis, occlusion, or aneurysm. "Interferon-gamma (IFN-γ) is a cytokine involved in the pathogenesis of Takayasu’s arteritis (TAK)." (PMID 34429489, 2021).
tendinopathy (4 papers, 2016 to 2025). "While some studies show little to no observable levels of IFNγ in acute Achilles tendon rupture 2 weeks postoperatively, others show increased expression of IFNγ in early stage tendinopathy samples of human subscapularis." (PMID 34350166, 2021). "Cytokines, such as interleukins, TNF-α, and interferon gamma are known to be key players in tendon disorders." (PMID 32075290, 2020). "The role of IFNγ in tendinopathy and healing remains poorly characterized." (PMID 34350166, 2021). "Other potentially interesting biomarkers for musculoskeletal diseases, such as tendinopathy, include TNF-α, interleukin 1 beta (IL-1β), basic fibroblast growth factor (bFGF), interferon gamma (IFN-γ), platelet derived growth factor BB (PDGF-BB) and vascular endothelial growth factor (VEGF)." (PMID 26925234, 2016). "Interestingly, proinflammatory and catabolic cytokines such as interleukin-1 beta (IL-1β), tumor necrosis factor alpha (TNF-α), and interferon gamma (IFN-γ) have been immunolocalized in horses with tendinopathy but not in healthy horses." (PMID 40284884, 2025).
thymic atrophy (4 papers, 2021 to 2024). "We previously showed that M. avium-induced thymic atrophy results from increased glucocorticoid levels that synergize with nitric oxide (NO) produced by interferon gamma (IFNγ) activated macrophages." (PMID 34987496, 2021). "M. avium infection-induced thymic atrophy arises from a synergy between glucocorticoids (GC) and nitric oxide (NO) produced by interferon gamma (IFNγ) activated macrophages (Mφ), since mice lacking IFNγ, iNOS or the activation of Mφ by IFNγ show no infection-induced thymic atrophy." (PMID 34987496, 2021). "Since the observed reduction on the percentage and number of CLP is independent of IFNγ and iNOS, this alteration was excluded as the mechanism responsible per se for M. avium-induced thymic atrophy; still it might synergize with other mechanisms yet to be identified." (PMID 34987496, 2021). "Additionally, BM from mice lacking IFNγ (IFNγKO), iNOS (iNOSKO) or the signaling of IFNγ in Mφ (MIIG), crucial factors that contribute to M. avium strain 25291 infection-induced thymic atrophy, were also analyzed after infection." (PMID 34987496, 2021).
thyrotoxicosis (4 papers, 2022 to 2025). A hypermetabolic syndrome caused by the elevation of thyroid hormone levels in the serum. "Studies demonstrate that levothyroxine treatment enhances NK cell activity and IFNγ production, but not in the case of thyrotoxicosis." (PMID 39940745, 2025).
VEXAS syndrome (4 papers, 2023 to 2025). An adult-onset inflammatory disease that affects only males and is caused by somatic, not germline, mutations. "Mutant myeloid cells are believed to drive the inflammation in patients with VEXAS syndrome, as analyses have revealed activated inflammatory pathways consistent with myeloid-induced inflammation, including tumor necrosis factor (TNF), interleukin-6 (IL-6), and interferon-gamma (INF-gamma)." (PMID 36879894, 2023).
acute liver failure (3 papers, 2016 to 2025). Rapid deterioration of liver function causing encephalopathy and coagulopathy. "IFNγ, which is associated with acute liver failure, exhibited higher levels in OLR at T1 in the liver, whereas RLR patients showed stable and slightly reduced postoperative levels in the blood, recovering by POD5." (PMID 41006707, 2025).
age (3 papers, 2014 to 2025). A temporal measurement of the time period elapsed since an identifiable point in the life cycle of an organism. "The improved profile can attenuate age-related inflammation (inflammaging) and, consequently, improve glucose metabolism in skeletal muscle, as well as suppressing activation of macrophages, IL-2, and interferon-gamma (IFN-γ)." (PMID 41141350, 2025).
anorexia nervosa (3 papers, 2019 to 2023). A disorder most often seen in adolescent females characterized by a refusal to maintain a minimally normal body weight, an intense fear of gaining weight, a disturbance in body image, and, in postmenarcheal females, the development of amenorrhea. "Many inflammatory cytokines are involved in anorexia nervosa, such as IL-1, IL-6, interferon-gamma (IFN-γ), TNF-α, and leptin." (PMID 35740622, 2022).
arteriosclerosis (3 papers, 2013 to 2019). A vascular disorder characterized by thickening and hardening of the walls of the arteries. "IFNγ signaling in smooth muscle cells is also important in the development of intimal thickening, as supported by findings that IFNγ is sufficient to cause intimal thickening by promoting vascular smooth muscle cell mitogenesis in a humanized mouse model of arteriosclerosis." (PMID 25628623, 2014).
autism spectrum disorder (3 papers, 2020 to 2023). A spectrum of developmental disorders that includes autism, and Asperger syndrome. "Some patients with autism spectrum disorders (ASDs) have an augmented level of proinflammatory cytokines IL-12, IL-6 and IL-1β, while IFNγ and the anti-inflammatory cytokine IL-10 seem to be reduced." (PMID 36835652, 2023).
bladder urothelial carcinoma (3 papers, 2022 to 2025). "al., which contains CALR, IFNB1, and IFNG, showed a powerful function in bladder urothelial carcinoma prognosis and immune landscape determination." (PMID 40557150, 2025).
breast invasive ductal carcinoma (3 papers, 2017 to 2023). "In this cohort, the most amplified gene is IFNG, which is 2.21% and mostly abandoned in breast invasive ductal carcinoma." (PMID 34196131, 2022).
choroidal (3 papers, 2012 to 2025). "Rejection of these ocular tumors is due to direct effects of IFNγ on tumors as Ad5E1 were also rejected in IFNγ receptor 1 (IFNγR1) deficient mice." (PMID 23060881, 2012). "As Ad5E1 tumors do not express MHC Class II these data suggest a model in which CD4+ T cells infiltrating ocular tumors express IFNγ only after engaging tumor Ags complexed with MHC Class II that are presented by ocular APC, most probably intratumoral macrophages." (PMID 23060881, 2012). "Hence, IFNγ is required for rejection of established Ad5E1 ocular tumors but not for protection from a subsequent ocular tumor challenge." (PMID 23060881, 2012). "The direct effects of IFNγ on Ad5E1 tumors include inhibiting proliferation, and inducing expression of the death inducing molecule TRAIL-R2 and several anti-angiogenic molecules which in combination leads to non-phthsical ocular tumor elimination." (PMID 23060881, 2012). "However, CD4+ T cell infiltration of ocular tumors does not appear to be compromised as Ad5E1 tumors are spontaneously rejected when placed in the a.c. by a process that requires CD4+ T cells, macrophages, and IFNγ." (PMID 23060881, 2012).
chronic bronchitis (3 papers, 2020 to 2024). A type of chronic obstructive pulmonary disease characterized by chronic inflammation in the bronchial tree that results in edema, mucus production, obstruction, and reduced airflow to and from the lung alveoli. "Patients with chronic bronchitis have reduced alveolar macrophage activity regardless of smoking history, and treatment with Broncho-Vaxom (OM-85), an oral capsule containing eight strains of bacterial extracts, significantly increased macrophage activity in the BAL, due to stimulation by IFNγ." (PMID 32948003, 2020).
chronic lung disease (3 papers, 2015 to 2021). According to the definitions of the American and British Thoracic Societies, including pulmonary functional tests, X-rays, and CT scans for items such as fibrosis, bronchiectasis, bullae, emphysema, nodular or lymphomatous abnormalities. "Interferon gamma (IFNγ) plays an important role in the development of chronic lung diseases via the production of inflammatory mediators, although the exact mechanism remains unclear." (PMID 31072323, 2019). "We have shown that these cells produce increased cytotoxic (granzyme b and perforin) and inflammatory (IFNγ and TNFα) mediators in several adult chronic lung diseases and hypothesised that similar changes would be evident in children with BE." (PMID 26258716, 2015).
cutaneous T cell lymphoma (3 papers, 2009 to 2024). "A study has shown that adenovirus vaccine injection into the tumoral lesions of cutaneous T-cell lymphoma leads to tumor reduction by the induction of interferon gamma, a subtype 1 helper T (Th1) cell cytokine." (PMID 23021252, 2012).
endometrial tumors (3 papers, 2017 to 2024). "Using The Cancer Genome Atlas (TCGA) data of MSI-H endometrial tumors, we found reduced expression of gene sets associated with interferon gamma, interferon alpha, IL-6, and IL-2 responses in JAK1 frameshift mutants compared to JAK1 wild-type tumors." (PMID 29121062, 2017). "Eight hallmark gene sets were significantly downregulated in JAK1 frameshift samples and five of those were reduced in endometrial tumor samples including IFNα, IFNγ, inflammatory response, allograft rejection, and coagulation." (PMID 29121062, 2017). "Five primary endometrial tumors were dissociated into a single-cell suspension and analyzed by flow cytometry for cell counts or incubated with MCLA-145 or reference antibodies in the presence of soluble anti-CD3 antibody to measure IFNγ production." (PMID 34290245, 2021).